MIR1286 (microRNA 1286)
Synonyms: hsa-mir-1286; MIRN1286; mir-1286
Gene: MicroRNA gene on chromosome 22 (20,249,134 to 20,249,211, reverse strand). Ensembl gene ENSG00000221039.
Homologues: Orthologues: chimpanzee ptr-mir-1286 (100% identical).